ERBB2 (erb-b2 receptor tyrosine kinase 2)
Diseases named in the same sentence as ERBB2 in open-access papers (continued):
Sharing a sentence is not in itself a finding about the gene and the disease.
breast cancer (continued). "Building upon the hypothesis that mRNA expression has a wide dynamic range, recent studies have explored quantitative ERBB2 mRNA levels as a means to develop a new assay for HER2-low breast cancer." (PMID 38297001, 2024). "However, the molecular mechanisms between miR‐449c‐5p and ERBB2 in breast cancer remain poorly understood." (PMID 38351535, 2024). "Indeed, PGC-1α promotes the growth of ErbB2/Neu-induced mammary tumors by modulating nutrient availability." (PMID 38424050, 2024). "The impact of chronic BPA intake was also investigated in a study performed using transgenic mice that spontaneously developed mammary tumors driven by the overexpression of wild-type ErbB2/neu (MMTV-ErbB2 mice) but after a longer latency and with a lower multiplicity as compared to BALB–neuT mice." (PMID 38892447, 2024). "Conversely, failure to achieve adequate suppression of cell proliferation was correlated with ERBB2 mutated, non-amplified breast cancer, in ILC." (PMID 39594781, 2024). "Given that Her-2 enriched breast cancer is a well validated, biologically distinct subtype with copy number amplification of the ERBB2 gene, we selected a clustering result which grouped HER2− enriched samples consistently into a single cluster to be used for all subsequent analyses." (PMID 38649964, 2024). "In a subgroup analysis, we found that ctDNA alteration detection in patients with HR-positive, ERBB2-negative breast cancer was associated with reduced survival (hazard ratio, 1.38; 95% CI, 1.15-1.61; P < .001) (eFigure 2 in Supplement 1)." (PMID 39235812, 2024). "For example, the kinesin-1 protein KIF5B is upregulated in highly invasive MCF7 breast cancer cells expressing constitutively active ErbB2, as compared to non-mutated MCF7-cells." (PMID 38474423, 2024). "Similarly, the most common GMT in either one of these groups (ERBB2/Her2-neu directed therapy in breast cancer; PD-1/PD-L1-targeted therapy in lung cancer) are commonly indicated and effective treatments for these two cancers." (PMID 38461318, 2024). "Interestingly, activated ErbB2-induced macropinocytosis-mediated cholesterol uptake in breast cancer cells is connected to upregulation of NPC1 and can thus be blocked by inhibiting it." (PMID 39243069, 2024). "The highly aggressive ERBB2/HER2-positive breast cancer accounts for 20% of all breast tumors." (PMID 38546612, 2024). "Although previous studies have demonstrated that G to A mutation at amino acid codon 655 of the human erbB-2/HER2 gene is a new allele polymorphism of the ERBB2 gene, the exact role of such mutation as a therapeutic target in luminal-like breast cancer remains further clinical elucidation." (PMID 38279318, 2024). "This aligns with existing literature that identifies chromosomes 17 and 11 as regions frequently involved in breast cancer progression, primarily due to the presence of oncogenes like ERBB2 (Her2) and CCND1, which are known drivers of cell proliferation and tumor growth through gene amplification." (PMID 39596229, 2024). "Similarly, in an in vitro breast cancer model, ErbB2 and MUC1 biCAR-T cells demonstrated potent anti-tumor activity." (PMID 38622705, 2024). "Consequently, this study aimed to assess the prognostic value of a 22‐gene mutational profile obtained via targeted sequencing of primary breast cancer specimens from patients with ER+/ERBB2‐ EBC archived in the tissue bank under an extended follow‐up." (PMID 39031010, 2024). "These instances, marked by late-stage, hormone receptor-positive, and ErbB2-negative cancers, highlight the intricacies and challenges associated with treating advanced breast cancer that manifests with unusual metastatic presentations." (PMID 39497719, 2024). "In this retrospective cohort study, age was an independent factor associated with late DR in young patients with ER-positive, ERBB2-negative breast cancer." (PMID 39509133, 2024).
breast cancer (continued). "According to guidelines of the American Society of Clinical Oncology (2018), breast cancer is HER2-positive if an analysis of biopsy samples from tumours shows 3+ staining by immunohistochemistry (IHC) or ERBB2 gene amplification of six or more copies via in situ hybridization (ISH) tests." (PMID 38675107, 2024). "In breast cancer, concurrent amplification of the CDK12 and ERBB2 genes has been described in ductal type NST carcinomas and in association with poor prognosis, worse response to anti‐HER2 treatment and also resistance to endocrine therapy." (PMID 38335502, 2024). "Further, an overexpression of EGFR/ErbB1 and especially ErbB2 is often found in breast cancer." (PMID 38896334, 2024). "Furthermore, we found that miR‐449c‐5p/ERBB2 inhibited the proliferation, invasion and migration of breast cancer cells." (PMID 38351535, 2024). "Caution is required when relying solely on pCR as a surrogate endpoint in clinical trials since this may not fully reflect long-term outcomes in the real-world setting, especially in ER+ErbB2- breast cancer, which is known for late recurrences." (PMID 39006626, 2024). "We also show that alteration of ERBB2 expression can drive A3A mRNA levels, suggesting the enrichment of the APOBEC mutation signature in Her2-enriched breast cancer could in part result from elevated A3A transcription." (PMID 38805570, 2024). "The goal of this study is to develop an improved assay for rapid, reproducible, accurate, and cost-effective ERBB2 CN estimation, and to evaluate the relationship of a more accurate estimation of ERBB2 CN to the response to trastuzumab across a large breast cancer patient cohort." (PMID 38374091, 2024). "Finally, we tested the ability of HER2DX ERBB2 mRNA expression to predict CelTIL response in an independent dataset of 20 patients with early-stage HR+/HER2− breast cancer treated in Part B of the trial." (PMID 38992028, 2024). "Thus, to analyse the contribution of NCAPH expression to the heterogeneous outcome of luminal ERBB2 breast cancer, we used a genetically heterogeneous cohort of MMTV‐ErbB2 transgenic mice generated by backcrossing (BX‐Neu+ mice after that)." (PMID 38344872, 2024). "In a study on breast cancer, centrosome amplification was found to trigger cell invasion, a behavior similar to that induced by the overexpression of the breast cancer oncogene ErbB2, and it further enhanced ErbB2-induced invasiveness." (PMID 39668833, 2024). "In HER2 positive breast cancer, ERBB2 (HER2) gene amplification is the most obvious." (PMID 38406813, 2024). "What is the quantitative association between pathologic complete response (pCR) and event-free survival (EFS) by intrinsic subtype and other gene expression signatures in patients with ERBB2/HER2-positive early breast cancer (EBC) treated in the neoadjuvant setting?" (PMID 38546612, 2024). "Furthermore, ErBb2-CAR modified NK92 cells exhibited strong killing effects on HER2-positive breast cancer and ovarian cancer cell lines, along with tumor growth inhibition in vivo." (PMID 39221244, 2024). "Perhaps one of the best examples is therapy targeting HER2/ERBB2 amplifications in breast cancer." (PMID 38999925, 2024). "This mouse was crossed to two models for ERBB2/NEU+ breast cancer: one based on expression of an oncogenic ErbB2/Neu cDNA downstream of the endogenous ErbB2 promoter (FloxNeoNeuNT), the other, a metastatic model that is based on high-level expression from MMTV regulatory elements (NIC)." (PMID 38807216, 2024). "ERBB2/HER2-low breast cancer is a novel category introduced in 2018." (PMID 38638322, 2024).
breast cancer (continued). "HER2 (encoded by ERBB2) is an oncogenic driver frequently altered in multiple cancer types, including breast cancer and malignancies of the gastrointestinal tract, where HER2-targeted therapies have improved patient outcomes and have received regulatory approvals." (PMID 38908022, 2024). "Furthermore, FOXP3 inhibits oncogenic ErbB2 overexpression by binding to the ErbB2 promoter, which ultimately inhibits breast cancer progression." (PMID 39668835, 2024). "This phenomenon likely explains why ERBB2‐amplified ILBC behaves in a more similar clinical manner to ERBB2‐amplified NST carcinomas as has been already postulated in sparse previous literature sources on NST breast carcinomas." (PMID 38335502, 2024). "The most common and widely accepted classification of breast cancer is from an immunohistochemical perspective, based on the expression of estrogen receptor (ER), progesterone receptor (PR), and overexpression of human epidermal growth factor receptor 2 (HER2), and/or amplification of ERBB2 gene." (PMID 39224777, 2024). "Breast cancer can be categorized into three primary subtypes, hormone-receptor-positive (HR+ BC), HER2-positive (HER2+ BC), and triple-negative (TNBC), based on the presence or absence of the estrogen receptor (ER), progesterone receptor (PR), and ERBB2 (commonly known as HER2)." (PMID 39000600, 2024). "Overexpression of ERBB2 (also known as HER2/NEU) is associated with human breast cancers, and mouse models of HER2+ tumors, including MMTV-NIC transgenic mice (expressing an activated oncogenic human ERBB2), have provided many insights into how ERBB2 induces tumors and promotes metastases." (PMID 38236941, 2024). "In contrast, ERBB2 gene amplification in feline mammary carcinoma ranges from only 0–4% of cases." (PMID 38787171, 2024). "Conversely, CDK12 is co-amplified with the receptor tyrosine kinase (RTK) oncogene HER2 (also known as ERBB2) in many cases of breast cancer, where it promotes migration and invasion of tumor cells by downregulation of the nuclear isoform of DNAJB6 via alternative last exon splicing." (PMID 37811895, 2023). "To further examine whether HER2 is responsible for neddylation-mediated breast cancer progression, we tested the signaling pathways related with ErbB2/NEDD8 using multi-omics analysis." (PMID 36632463, 2023). "The CLEOPATRA trial showed that for HER2+ breast cancer that overexpresses HER2 or has ERBB2 (HER2) gene amplification, 16% of patients were progression-free at 8 years and could be effectively treated." (PMID 37958607, 2023). "Which immune-related biomarker provides the most valuable information to predict pathologic complete response and event-free survival in patients with early-stage ERBB2/HER2-positive breast cancer: tumor-infiltrating lymphocytes, immune-related gene expression signatures, or both?" (PMID 36602784, 2023). "Trastuzumab has improved overall survival outcomes for ERBB2+ breast cancer." (PMID 37359373, 2023). "Amplification of the HER2 gene (ErbB2) and corresponding overexpression of the HER2 receptor occurs in approximately 20–25% of breast tumors and is associated with a worse prognosis, shorter disease-free, and overall survival in breast cancer." (PMID 38067203, 2023). "Breast cancers can be categorized into three major subtypes on the basis of the hormone receptors: estrogen receptor (ER) positivity, progesterone receptor (PR) positivity and human epidermal growth factor 2 (HER2, also known as ERBB2) positivity." (PMID 38052873, 2023). "CP724714, a selective (ErbB2; Her-2/neu) tyrosine kinase inhibitor to inhibit ErbB2 receptor autophosphorylation in intact cells, has been used in breast cancer cell lines and SKOV3 ovarian cancer cells, which had significant decline on both survival after treated with CP724714." (PMID 36768349, 2023).
breast cancer (continued). "Whereas ERBB2 is commonly overexpressed in canine mammary tumors, there is no clear association between its protein status and histological grade, clinical parameters or prognosis." (PMID 37219601, 2023). "Breast cancer with lymph node metastases were in general associated with lower levels of the CSC genes ALDH1A3 and CD44, pluripotency markers POU5F1 and NEAT1, EMT marker SLUG, and drug resistance associated gene ERBB2, after DOX treatment." (PMID 38124067, 2023). "In addition to ERBB2, other LDE genes identified by POLARIS and the proteins encoded by those genes also play important roles in breast cancer." (PMID 36857450, 2023). "Repeated intratumoral injections of CAR-modified T cells specific to erbB-2 accumulated cells at tumor sites have eliminated tumor cells as well as prevented relapse in a mouse spontaneous mammary tumor model due to overexpression of the human erbB-2 transgene." (PMID 38006049, 2023). "Similarly, a label-free immunosensor for the detection of the breast cancer biomarker, epidermal growth factor receptor 2 (ErbB2), was reported." (PMID 37185491, 2023). "Both tumor-infiltrating lymphocytes (TILs) assessment and immune-related gene expression signatures by RNA profiling predict higher pathologic complete response (pCR) and improved event-free survival (EFS) in patients with early-stage ERBB2/HER2-positive breast cancer." (PMID 36602784, 2023). "MZF1 is a transcription factor that regulates ErbB2-induced invasion of breast cancer cells by inducing expression of cathepsin B (CTSB) and the outward transport of lysosomes to the plasma membrane, where the exocytosis of cathepsin B and other lysosomal hydrolases contribute to cancer invasion." (PMID 37420029, 2023). "To conclude, accumulating evidence supports the validity of using evidence of immune activation, which can be measured with TILs or immune-related gene expression biomarkers, to stratify patients with early-stage ERBB2/HER2-positive breast cancer into different prognostic groups." (PMID 36602784, 2023). "Similarly to many human HER2+ breast cancers, it overexpresses the wild type form of Erbb2, which develops slowly, starting from foci of hyperplastic, dysplastic mammary epithelium and progressing to aggressive metastatic carcinoma." (PMID 36831460, 2023). "Interestingly, slight ERBB2 expression was found in the luminal subtype, and the results were compatible with the previous studies on clinical trials that ERBB2-targeted therapy demonstrated better survival in patients with HER2-low breast cancer." (PMID 37759508, 2023). "Thus, the aim of this work was to evaluate the efficacy of PPRHs against the ERBB2 gene in HER-2-positive breast cancer cell lines, alone or in combination with the antibody trastuzumab, both in vitro and in vivo." (PMID 37108234, 2023). "However, there are groups of ERBB2+ breast cancer, lung cancer, esophageal cancers, and gastrointestinal cancers that are resistant to trastuzumab and tyrosine kinase inhibitors." (PMID 37359373, 2023). "Gene amplification and coexpression of PNMT and ERBB2 have been observed in breast cancer patients." (PMID 36984849, 2023). "Targeted therapies have proven tremendously effective to treat HER2 (ERBB2)-positive breast cancer." (PMID 36670508, 2023). "Therefore, the relevance of ERBB2 in breast cancer well motivates its prominence within the scientific discourse." (PMID 37768281, 2023). "Our aim was to investigate whether ERBB2-low breast cancer is a clinically distinct subtype in terms of epidemiological characteristics, prognosis, and response to neoadjuvant chemotherapy." (PMID 36821125, 2023). "One study used FVB strain erbB2 (HER2) mutant mice with genetic prepositions to mammary tumors and found that when supplied with Lactobacillus reuteri to the gut, the mouse immune system triggered CD4+CD45RBloCD25+ lymphocyte (Treg cells) protective mechanisms to inhibit cancer progression." (PMID 37664075, 2023).
breast cancer (continued). "While these diagnostic procedures are standard of care in breast cancer and gastric cancer, where ERBB2 is a more frequent target, mCRC patients are not regularly screened for ERBB2 alterations in most centers." (PMID 38138928, 2023). "ERBB2 is an important factor in breast cancer in human medicine." (PMID 37859946, 2023). "A randomized phase 2 I-SPY2 trial examined the efficacy of neoadjuvant treatment that included pembrolizumab, on participants with early-stage, high-risk, ERBB2 (formerly HER2)-negative breast cancer." (PMID 36875096, 2023). "Activation of the ERBB/HER family of proteins has been repeatedly implicated in oncogenesis and can be induced by various molecular alterations, including EGFR point mutations or short insertions or deletions (indels) in NSCLC and ERBB2 amplification in breast cancer." (PMID 37168365, 2023). "Whether there is a molecular basis that could explain these subtle differences in survival and chemotherapy responsiveness in ERBB2-low breast cancer remains to be ascertained." (PMID 36821125, 2023). "To study the tumour suppressor role of KMT2C in breast cancer, we generated mouse models of Erbb2/Neu, Myc or PIK3CA-driven tumorigenesis, in which the Kmt2c locus is knocked out specifically in the luminal lineage of mouse mammary glands using the Cre recombinase." (PMID 36933062, 2023). "Indeed, we find that vehicle-treated ErbB2-induced breast cancer tissue expresses Il1a, Il1b, Il6, and Nfkb1 at a measurable level." (PMID 37098526, 2023). "HER2+ breast cancers are further characterized by ERBB2 amplification." (PMID 37239141, 2023). "For breast cancer patients, ER and erbB2 are important prognostic markers and therapeutic targets." (PMID 36766896, 2023). "These promising results demonstrate the potential for effective cancer vaccines and how these could offer a novel treatment option for patients with advanced-stage ERBB2-positive breast cancer." (PMID 36980723, 2023). "In clinical practice, ErbB2 is an established therapeutic target for ErbB2-positive breast cancer." (PMID 37508418, 2023). "In the group exposed to anti-ERBB2 agents, most reports were from the US (159 [48.5%]), the mean (SD) age of participants was 30.8 (10.4) years, and 209 patients (97.7%) were treated for breast cancers." (PMID 37883083, 2023). "To explore further the consequences of carbonic anhydrases in breast cancer and focus explicitly on our unexplained findings from HER2-enriched breast cancer, we next perform functional experiments on human breast cancer tissue and in a mouse model of ErbB2-induced breast cancer." (PMID 37098526, 2023). "Our results show the crucial roles of Shc3 and ErbB2 in modulating P‐gp efficacy in breast cancer cells and suggest that Shc3 inhibition may enhance the sensitivity to chemotherapeutic drugs that target oncogene addiction pathways." (PMID 36880347, 2023). "Furthermore, for the HR–/ERBB2+ subtype, younger patients with breast cancer had a distinct timing for developing CBC compared with older patients." (PMID 38100108, 2023). "In patients with basal-like/triple-negative breast cancer, elevated expression of the extracellular carbonic anhydrases negatively predicts survival, whereas, surprisingly, the extracellular carbonic anhydrases positively predict patient survival in HER2/ErbB2-enriched breast cancer." (PMID 37098526, 2023). "Taken together, we demonstrate that by destabilizing ERBB2, we controlled and downregulated YES1 and WNK1 that are well-known causes of drug resistance in ERBB2+ trastuzumab drug-resistant breast cancer and in osimertinib-resistant EGFR T790M lung cancer, respectively." (PMID 37359373, 2023).